CD40 (CD40 molecule)
Diseases named in the same sentence as CD40 in open-access papers (continued):
Sharing a sentence is not in itself a finding about the gene and the disease.
cancer (continued). "One important highlight is the observation that HDAC inhibition could improve cancer cells’ immune response via the regulation of the expressions of tumor antigens, including CD40, CD80, CD86, MHC, ICAM-1 and MICA/B, which drive the elimination of cancer cell proliferation through the immune system." (PMID 35158821, 2022). "The fact that CD40 is recovered either by proteasome inhibition or E6 ablation in HeLa cells, indicates a possible role for CD40 in the modulation of immune surveillance and represents basic findings for the study of CD40 novel actions in the development of HPV derived cancers." (PMID 30562965, 2018). "The finding that sCD40L failed to induce NORE1A expression in any of the examined CD40-expressing carcinomas prompted us to examine whether sCD40L retains its full biological activity and was capable of activating the CD40 receptor." (PMID 26986513, 2016). "The agonistic CD40 mAb has not been universally accepted as a novel cancer therapy." (PMID 25651850, 2015). "Because CD40+ MDSC accumulates in gastric, lung and prostate xenograft tumors, it would be interesting to examine whether the CXCR5-CXCL13 axis is equally important for MDSC recruitment in other cancer types." (PMID 26462153, 2015). "CD40 is expressed on the surface of immune cells or non-immune cells such as B cells, monocytes, endothelial cells, epithelial cells, mesenchymal cells, platelets and malignant tumor cells." (PMID 24337678, 2014). "Interestingly, binding of CD40L by CD40 induces the apoptosis of cancer cells, but not of the healthy ones." (PMID 25117071, 2014). "Importantly, induction of CD40 signaling on DCs using, for example, agonistic antibodies can substitute for CD4+ T-cell help and directly stimulate a specific CD8+ CTL response, highlighting a clear rationale for CD40-based cancer immunotherapy." (PMID 23840967, 2013). "Although clinical translation of these findings for patients with cancer has been previously limited due to the lack of a suitable and available drug, promising clinical results are now emerging from phase I studies of the agonist CD40 monoclonal antibody CP-870,893." (PMID 19906293, 2009). "The association between CD40 and APC was also evaluated using the TCGA Pan-Cancer Atlas cohort, confirming that APC alterations were significantly more frequent in the non-high CD40 group than in the high CD40 group." (PMID 41182434, 2025). "Cancer-free LNs harbour fewer CD4+ T cells, CD8+ T cells, CD80+, CD86+ and CD40+ immune cells and DCs which do not show characteristics associated with effective antigen presentation." (PMID 36139665, 2022). "Previous studies showed that unlike anti-CD40 antibodies or soluble CD40L, the natural trimerized form of CD40L, e.g., expressed on the membranes of antigen-activated T cells, mediates cytotoxicity in cancer cells to a high degree." (PMID 40397730, 2025). "Being a non-classical TNFR, CD40 has been reported to engage the intrinsic, mitochondrial pathway of apoptosis which requires >6–12 h before Bak/Bax induction and mitochondrial outer membrane permeabilization (MOMP) as observed in some cancer cell types." (PMID 36291141, 2022). "Collectively, these findings highlighted the importance of the mode of CD40 ligation in determining functional outcome in carcinoma cells, and provided an explanation for lack of detectable pro-apoptotic effects in RCC cells in previous studies which employed soluble CD40 agonists." (PMID 31815003, 2019). "Furthermore, the ability of elderly DCs to respond to activation via CD40, which is important for DCs to gain full APC function, as well as representing a promising approach for anti-cancer immunotherapy, has not yet been reported." (PMID 29652910, 2018).
cancer (continued). "Treatment with CD40 ligand decreased proliferation of BT-20 and T-47D cells which are CD40-positive, but did not change the growth of CD40-negative breast cancer cell lines, as detected in MCF-7 or ZR-75-1 cells, supporting the idea that CD40–CD40LG axis modulates proliferation of cancer cells." (PMID 32256143, 2020).
infection (261 papers, 2006 to 2026). The state of being infected such as from the introduction of a foreign agent such as serum, vaccine, antigenic substance or organism. "Our mechanistic investigations revealed that TLR2 promotes H. pylori uptake and the enhanced CD40 expression upon infection with the ADP-heptose deficient H. pylori mutant." (PMID 39288239, 2024). "CD40−/− mice were significantly more susceptible to infection with a recombinant vesicular stomatitis virus (VSV) that encodes Ebola virus glycoprotein (rVSV-EBOV GP)." (PMID 37376652, 2023). "In contrast, mice deficient for the co-stimulatory molecule CD40 experienced persistent infection and the depletion of CD11c+ DC delayed pathogen clearance." (PMID 33747981, 2021). "At the beginning of the infection, the susceptible mice developed better fungal growth control, with high NO and IL-12 production levels and increased expression of CD40, but with disseminated disease and low mice survival rate." (PMID 33796477, 2021). "The increased expression of the DC surface marker CD40 caused by V. vulnificus wild-type infection was reduced by rtxA gene mutation in V. vulnificus." (PMID 30283443, 2018). "CD40 has been implicated in both P. aeruginosa and S. pneumoniae infection, while PEDF (SERPINF1) is known to inhibit angiogenesis and acts as a neurotrophic factor in neuronal differentiation." (PMID 24086587, 2013). "Additionally, WT mice that were treated with an agonistic CD40 antibody 24 h prior to infection exhibited decrease susceptibility to viral challenge." (PMID 37376652, 2023). "Although classical co-stimulatory molecules such as CD80 and CD8613,18,41,42 are expressed at low levels, CD40 is upregulated on PMVECs after infection, as confirmed in vivo and in vitro." (PMID 41542053, 2026). "In the case of co-stimulatory molecules, Cd40 and Cd86 were both upregulated by infection, with IFNγ further amplifying this effect." (PMID 40547518, 2025). "CD40 in particular is important for the restriction of infection of a broad range of RNA viruses and is critical for the control of RNA viruses over the first 24 h of infection." (PMID 38674902, 2024). "In contrast, for baboons receiving anti-CD154 antibody-based or anti-CD40 protocols, the experiments were terminated mainly because of infection or other complications." (PMID 38391160, 2024). "TRAIL‐R1 and 2 were both significantly upregulated post infection with a TMZ‐CD40L‐containing LOAd virus in the CD40‐positive cell lines even if several other lines tended to upregulate these receptors as well." (PMID 38494863, 2024). "Clinical studies testing in humans the potency of CD40.COVID vaccines as booster of pre-existing immunity, induced either by previous priming with available vaccines or natural infection, are planning in 2024." (PMID 39667270, 2024). "Similar to infection with the H. pylori ΔrfaE mutant, infection of DCs with A. lwoffii resulted in enhanced secretion of IL-12p70 as well as CD40 expression compared to infection with H. pylori wt." (PMID 39288239, 2024). "Along the course of infection, there was a reduction in the expression of M1 markers like Nos2, Cd40,Cd86, Tnfa, Nfkb2, Il6 and a corresponding increase in the expression of the M2 markers such as Arg1, Ccl17, Cd206, IL4ra with an exception of Tgfb." (PMID 39693143, 2024). "Though susceptible to only an abortive infection, DCs experimentally infected with FMDV have been shown to downregulate CD40 expression, failing to stimulate T cell proliferation and leading to a dysfunctional T cell response early in FMDV infection." (PMID 38638908, 2024). "rBCG-Rv1002c infection significantly upregulated immune regulatory molecules on the macrophage surface, including CD40, CD80, CD86, and MHC-II." (PMID 38932351, 2024).
infection (continued). "Unfractionated splenocytes, as well as purified B cells, were able to control Pneumocystis infection, while B cell depleted splenocytes and unstimulated bone-marrow derived dendritic cells (BMDCs) were unable to control infection in CD40 KO mice." (PMID 38410485, 2024). "D609‐treated BMDCs exhibited a significant reduction in the mean fluorescence intensities of costimulatory molecules, including CD80, CD86, CD40, and the differences in the reduced levels of costimulatory molecules were more pronounced after infection." (PMID 39692711, 2024). "The combination treatment with both TMAO and CFT073 had significant additive effects on the release of PD-L1 and STAMBP and synergistic effects on the release of CDCP1, uPA, AXIN1, MMP-10, and CD40 compared to CFT073 infection alone." (PMID 37111409, 2023). "Our prior study demonstrated that loss of CD40 in purified pMφs enhances the virus load of VSV, Sindbis virus, IAV, EBOV, and Ross River virus at 24 h of infection and even as early as 12 h in in vivo studies with rVSV-EBOV GP." (PMID 37376652, 2023). "Given that CD40 plays a critical role in protecting mice during PR8 infection and that we saw a similar effect previously with rVSV-EBOV GP, we sought to evaluate the mechanism by which this occurs in vivo." (PMID 37376652, 2023). "On day 14 following infection, a reduced CD40 expression on pulmonary DCs was observed in rIL-27-treated mice when compared to PBS-treated mice." (PMID 36985179, 2023). "Evidence from the literature indicates that the targeted delivery of an antigenic protein (either HIV or SARS-CoV-2 proteins) to CD40 positive cells enhance the immune response, allowing for an early protection against infection." (PMID 37751460, 2023). "We find that stimulation of CD40 signaling decreases early IAV titers, whereas loss of CD40 elevated early titers and compromised lung function by day 3 of infection." (PMID 37376652, 2023). "CD40 expression levels were significantly (p ≤ 0.01) decreased in the duodenum, jejunum and ileum post infection with C. perfringens." (PMID 38164397, 2023). "Infection with C. perfringens in those chickens that had prior treatment with rL. lactis resulted in a significant (p ≤ 0.01) increase in CD40 expression in comparison to C. perfringens infected only chickens." (PMID 38164397, 2023). "Human blood-derived CD1c+ mDCs are susceptible to infection with BCG, up-regulating CD40, CCR7, HLA-DR, CD86 and other maturation markers, as well as producing TNF-α and IL-6." (PMID 37475964, 2023). "Despite this discrepancy between infection and infection/transfection methods, at least one optimized CD40 or 4-1BB agonist and PDL1 blocker have been obtained for vectorization into vaccinia virus." (PMID 38053848, 2023). "Following infection, testosterone-treated macrophages exhibited a gradual decrease in CD40 expression based on comparisons of 0, 80, and 160 nM groups (p = 0.04)." (PMID 37505653, 2023). "When CD40-sufficient pMφs were introduced to the peritoneal cavity of Ifnar−/−CD40−/− mice, we found that the presence of CD40-expressing Mφs was sufficient to protect mice from succumbing to infection." (PMID 37376652, 2023). "Our studies in pMφs found that CD40 signaling inhibits a variety of different RNA viruses as early as 12 h following infection." (PMID 37376652, 2023). "We observed that upon BPM treatment, the innate cells expressing co-stimulatory and activation markers, such as CD80, CD86, and CD40, were enhanced at the primary site of infection, i.e., lungs." (PMID 37272833, 2023). "We observed that MVA∆E5R-OVA infection induced higher levels of CD86 and CD40 expression compared with MVA-OVA at 24 h post-infection." (PMID 37217469, 2023). "The recombinant viruses were used to infect HeLa cells, and the culture medium obtained after 48 h of infection were tested for CD40 agonist activity." (PMID 38053848, 2023).
infection (continued). "Conversely, agonistic CD40 antibody stimulation of the pathway suppresses infection by these viruses." (PMID 37376652, 2023). "Our earlier studies demonstrated that the stimulation of CD40 signaling protects pMφs ex vivo from infection with a mouse-adapted strain of IAV (Puerto Rico/8/34 or PR8)." (PMID 37376652, 2023). "The CD40 and CD40 ligand interaction is known to regulate a wide range of immunological events, including infection-induced inflammatory response, CD8 T cell senescence and increased viral replication." (PMID 36532041, 2022). "CD40-induced IL-10 promotes Leishmania infection whereas CD40-induced IL-12 protects hosts from infection." (PMID 35651757, 2022). "The CD40–CD40L interaction upregulates key proinflammatory molecules, a function best understood in the context of infection, during which B-cells are activated via CD40 signaling to produce antibodies." (PMID 35456932, 2022). "Our study uncovered a novel CD40-dependent Tfh1 axis with potential physiopathological relevance to infection." (PMID 36254574, 2022). "Our results indicated that infection status influences CD40 expression, showing downregulation in untreated MDMs from clinical cows when compared to controls (P < 0.001) and subclinical cows." (PMID 35111692, 2021). "Independently of infection, expression of M1-like markers CD40 and HLA-DR was significantly increased on macrophages retrieved from the 2D model." (PMID 34603299, 2021). "We previously showed that archived antigen obtained from the polyI:C/anti-CD40-based vaccine is transferred from LECs to migratory Batf3-dependent cDC1s 2 weeks after infection." (PMID 33843587, 2021). "CD40–/– mice exhibited lower parasite load in the brain and retina since the initial stages of infection with T. gondii, suggesting that CD40 restricts invasion of these organs." (PMID 34179003, 2021). "There appeared to be a tendency for an increase in the mean fluorescence intensity (MFI) of CD40 expression on all three monocyte subsets as a function of time post infection from D −2 to D +2." (PMID 34832614, 2021). "In the Rejection group, 5 baboons received conventional immunosuppressive therapy, and only one received an anti-CD40mAb-based regimen, whereas all 3 baboons in the Infection group received the anti-CD40 mAb-based regimen." (PMID 34956220, 2021). "Treated and untreated infected mice were sacrificed 96 hours and 2 weeks after infection, their lungs removed, macerated and CD11c+ lung myeloid cells analyzed by flow cytometry for the expression of activation markers (IAb, CD40, CD80, and CD86)." (PMID 33936043, 2021). "Confirming data with in vitro infection of BMDCs with mOVA2, local DCs acquired maturation markers (CD40 and CD86), with CD40 being the most responsive." (PMID 31988324, 2020). "In contrast, BMDC infection with LDPm or LDAm resulted in a temporal reduction in LPS-stimulated CD40 expression, with maximum inhibition occurring at 24 h postinfection." (PMID 33370418, 2020). "CD40+ B cells are more frequently infected with MHV68 than their CD40- counterparts at late stages of infection in CD40+/− mixed bone marrow chimeric mice." (PMID 32717815, 2020). "We investigated the impact of infection and parasite opsonization on the TLR/NLRP3-activated, canonical NF-κB pathway, and on the CD40/TNFRSF1b-activated, alternative NF-κB pathway linked to cross-presentation." (PMID 32582184, 2020). "mOVA2 infection led to the upregulation of DC maturation markers (CD40/80/86) and PD-L1 in a pattern that was qualitatively similar, but quantitatively diverging in FLT3L- vs. GMCSF-BMDCs." (PMID 31988324, 2020). "We found that BMDC infection with LDPm for 24 h also inhibited the CD40 upregulation induced by TNFα." (PMID 33370418, 2020). "Alternatively, additive stimulation of CD40 with proper timing would facilitate the generation of CD80hi Bmem cells that rapidly produce highly specific Abs upon actual infection." (PMID 31225793, 2019).
infection (continued). "The infection group showed a notable increase in the expression of CD40, CD80, CD86, and MHC class II." (PMID 30791397, 2019). "Specifically, CD40 is up-regulated on hepatocytes during infection with hepatitis C virus, can inhibit HCV replication and mediate viral clearance, and disruptions by activated innate immune mechanism." (PMID 31615434, 2019). "In the infection context, interference with CD40 upregulation can be expected to affect in particular inflammatory DCs, for which GM-CSF–BMDCs are a model." (PMID 31570562, 2019). "CD40-induced IL-10 promotes Leishmania infection whereas CD40-induced IL-12 protects hosts from the infection." (PMID 30609697, 2019). "In fresh whole blood, less than 1% of pDC expressed CD86, CD40 or CD80 before infection or at peak parasitaemia." (PMID 28572564, 2017). "Consistent with this, both ΔN146 infection and LPS treatment dramatically stimulated the expression of CD40 and CD86 as indicated by enhanced fluorescence intensities." (PMID 28150813, 2017). "CD163+ cells showed higher infection (MFI = 913.167) than CD40+CD163- (MFI = 715.143) cells (p = 0.0044, Friedman paired test)." (PMID 28355218, 2017). "In our previous study, we observed that infection by L. amazonensis in addition to decrease CD40 expression, also inhibited the expression of MHCII and CD86." (PMID 28791011, 2017). "ΔN146 infection and LPS stimulation significantly increased the population of CD11c+ CD40+ cells to 25.6% and 43.7%, respectively." (PMID 28150813, 2017). "In follow-up studies in a murine model of intranasal Chlamydia trachomatis infection, we analogously found that LNG treatment prior to infection dramatically reduced CD40 expression in DCs isolated from draining lymph nodes at 2 days post infection (dpi)." (PMID 27892938, 2016). "Our observations of CD40 affecting STING expression and IFN-I production in the early hours of infection add a new function to CD40, in addition to its known functional roles in CD8+ T-cell activation and IgG isotype switching during host adaptive response." (PMID 27716849, 2016). "In separate experiments, mice received LNG or matching placebo pellet 5 days before infection, while other LNG-pelleted mice received agonist anti-CD40 monoclonal antibody 1 day after infection." (PMID 27892938, 2016). "Infection of mixed CD40-/-/WT chimeras revealed a defect in the long-term maintenance of latency in CD40-/- but not WT cells." (PMID 27582728, 2016). "Surprisingly, while proportions of B cells expressing PD-L1 similarly increased, those expressing ICOSL were reduced whereas the ligand pair CD40:CD40L remained unchanged across the three infection groups." (PMID 27994594, 2016). "Other LNG-pelleted mice received agonist anti-CD40 antibody 1 day after infection, while other placebo-pelleted mice received CD4+ cell-depleting mAb 1 day prior to infection and for the duration of the study." (PMID 27892938, 2016). "Splenic cDCs expressed significantly higher levels of CD40 during infection, however, consistent with previous work, MHC class II and CD86 expression remained unchanged compared with naive controls." (PMID 26657145, 2016). "In the present study, we demonstrate that sCD40L in the serum of individuals exposed to L. infantum infection can bind to CD40 on L. infantum-infected macrophages and that it helps to control the infection." (PMID 26488744, 2015). "In numerous infectious diseases, the interaction of CD40 and CD40L can determine resistance or susceptibility to infection." (PMID 26488744, 2015). "This recombinant virus successfully infects human peripheral B-cells as seen by a strong GFP signal during early primary infection and also activated CD40 in a time-dependent manner." (PMID 26336822, 2015). "Our results also showed that an EBNA3C deficiency substantially decreases the CD40 activation in B-cells, indicating that EBNA3C has a role in driving EBV infected B-cells during early infection." (PMID 26336822, 2015).